ZEB1 (zinc finger E-box binding homeobox 1)
Diseases named in the same sentence as ZEB1 in open-access papers (continued):
Sharing a sentence is not in itself a finding about the gene and the disease.
tumor (continued). "miR-200 mediated inhibition of ZEB1 sensitizes KRAS mutant NSCLC cells to MEK inhibition and reduces in vivo tumor growth of NSCLC." (PMID 33898432, 2021). "Compared with the NC tumours, the protein level of CD11b and CD14 greatly increased in ZEB1 knock‐down tumours, while the expression of cyclin D1, cyclin A2, p‐Rb and CDK4 was markedly decreased in ZEB1 knock‐down tumours." (PMID 33960640, 2021). "Another report shows that miR-200 and miR-205 members can mediate EMT suppression by direct inhibition of ZEB1 and ZEB2, thus enhancing the tumour sensitivity to therapeutic interventions." (PMID 34868979, 2021). "Taken together, we identify ZEB1 and ZEB2 as EMT genes correlated with PRRX1 and assumingly acting with it to influence tumour characteristics." (PMID 34496784, 2021). "By targeting the zinc-finger E-box binding homeobox 1 and 2 factors (ZEB1 and ZEB2), E-cadherin and Bim1, miR-200b maintains the epithelial phenotype and suppresses cell proliferation, EMT, and tumor invasiveness." (PMID 33805590, 2021). "ZEB1 and ZEB2 are EMT transcription factors which synergistically increase tumor invasion and cell migration." (PMID 34201896, 2021). "Studies of prostate cancer have shown increased marker expression of EMT and Notch1, including vimentin, N-cadherin, ZEB1 (Zinc-finger E-box binding homeobox), NF-κB, and PDGF-D in tumor cells." (PMID 33670230, 2021). "We validated the expression of ZFAS1, identifying it as a major regulator of tumor progression in CRC, through the critical miR-200/ZEB1/E-cadherin, vimentin signaling cascade." (PMID 33771981, 2021). "MiR-145 was established as a tumor suppressor, targeting embryonic transcription factors including Lin28, Nanog, Sox2, and Oct4, and also inhibiting the EMT key regulator, ZEB1 expression." (PMID 34760707, 2021). "For example, hyperactivation of the IL6/JAK/STAT3 pathway promotes tumor metastasis and chemoresistance via induction of EMT through the upregulation of EMT-inducing transcription factors, such as Snail, Twist-1 and ZEB1." (PMID 34944855, 2021). "A previous study identified a relationship between the expression of mesenchymal genes in tumor cells (e.g., SNAI1, TWIST1, and ZEB1) and the extent of clearance." (PMID 34396026, 2021). "Expression of ZEB1, BMI1, and ALDH1A1 was analyzed by immunohistochemistry in tumor specimens from NSCLC patients with acquired resistance to gefitinib." (PMID 33764690, 2021). "There are many transcription factors involved in the occurrence of tumor EMT, such as Snail/Slug family, Twist, EF1/ZEB1, SIP1/ZEB2 and E12/E47." (PMID 34517345, 2021). "Nevertheless, similarly to the GSC cultures, we found a strong association between high Gln/Glu ratios and increased expression of ZEB1 and xCT in primary GBM tumor tissues." (PMID 34885110, 2021). "Consistent with the findings of the preclinical study using silibinin, silencing of ZEB1 restored miR‐200c expression in GRP tumor model in our study, along with reduced tumor incidence and slower tumor growth in vivo." (PMID 33764690, 2021). "Among them, cyclin-dependent kinase 6 (CDK6) and ZEB1/ZEB2 were essential regulators in cell cycle and metastasis of tumor cells, respectively." (PMID 34796112, 2021). "The exogenous signal that promote tumor growth can inhibit the expression of E-cadherin and mediate EMT by forming complex with transcription factors such as Snail, Slug, ZEB1, SIP1 and Twist and binding to the promoter of the CDH1 gene." (PMID 33992097, 2021). "ATM also mediates phosphorylation and stabilization of Zinc finger e-box binding homeobox 1 (ZEB1) a transcription factor driving EMT, tumor invasion, metastasis, and therapy resistance." (PMID 34638302, 2021). "Our results suggest not only that a novel ceRNA network between Snail and Zeb1 is regulated by miR-34a and miR-200, but, conversely, that the non-coding EMT gene UTRs dynamically regulate the tumor suppressive miRs." (PMID 34502497, 2021).
tumor (continued). "Previous studies have shown that ZEB1 is highly expressed in HCC and that its overexpression promotes tumor cell migration, invasion and metastasis through EMT." (PMID 33833131, 2021). "The expression rates of Zeb1, Twist, E-cadherin, N-cadherin, and β-catenin in LSCC correlated with lymphatic invasion and pathological tumor node metastasis." (PMID 34283055, 2021). "IL-6 aids in EMT via JAK-STAT3 or NF-κB pathways by activating EMT-TFs such as Snail, Slug, Twist, and Zeb1 which in turn reduces expression of CDH1 that drives migration and invasion of the tumor." (PMID 34220337, 2021). "Compared with the primary tumor, in the metastasis group, the mesenchymal markers (CDH2, VIM, TWIST1, SNAI1, ZEB1) and ferroptosis drivers increased, and the epithelial marker CDH1 and ferroptosis suppressor decreased." (PMID 35127731, 2021). "In primary TNBC samples high ZEB1 expression was correlated with upregulated JAG1 and Notch activity in invasive tumour regions." (PMID 34295896, 2021). "miR-101 has been reported to act as a tumor suppressor by targeting CDH1 inhibitors, such as ZEB1/ZEB2 and EZH2 in different tumors." (PMID 34943943, 2021). "The ZFAS1 gene is frequently amplified in HCC, which promotes metastasis through sponging tumor-suppressive miR-150 and then activating ZEB1 (zinc finger E-box-binding homeobox 1), MMP14 (matrix metallopeptidase 14), and MMP16." (PMID 34072570, 2021). "Taken together, these findings indicated that ZEB1, BMI1, and ALDH1A1 were highly expressed in tumor specimens from NSCLC patients with acquired resistance to gefitinib." (PMID 33764690, 2021). "We and others have showed that ZEB1 was highly expressed in HCC and its high expression was correlated with advanced TNM stage, tumor size, intrahepatic metastasis, vascular invasion, and frequent early recurrence." (PMID 33897890, 2021). "It is involved in the regulation of multiple tumor signaling pathways, such as PI3K/AKT, PTEN, JAK/STAT, TRPS1/ZEB1 and EMT." (PMID 35054253, 2021). "Recently, it has been shown that the disruption of miR-200/Zeb1 is sufficient to induce an effect on EMT and tumor progression." (PMID 34722255, 2021). "Overexpression of ZEB1 also induced resistance to gefitinib in vivo, as observed in the PC9 xenograft tumor model." (PMID 33764690, 2021). "On the other hand, we studied the mechanisms of UTMD-induced oxidative stress on the tumor EMT process and demonstrated that ROS induced by UTMD inhibited EMT through the regulation of the miR-200c/ZEB1 axis." (PMID 32313093, 2020). "Noteworthy, numerous neoplastic cells were scattered throughout the tumor area and expressed the EMT-related transcription factors TWIST-1, ZEB-1, and HIF-1α." (PMID 33297475, 2020). "The miR-200 family, composed of miR-200a, miR-200b, miR-200c, miR-141 and miR-429, mainly inhibits EMT by targeting the 3 'UTRS of ZEB1 and ZEB2 to inhibit tumor invasion and metastasis 5, which is considered as a tumor suppressor miRNA." (PMID 32226520, 2020). "Using human clinical tumor samples and a human SCC cell line, we found that the OVOL2/ZEB1 axis was crucially involved in the development of cSCC." (PMID 32106476, 2020). "It is well known that SNAI1, SNAI2, ZEB1, ZEB2, TWIST1 and TWIST2 are key transcription factors involved in EMT in various types of cancers, and they contribute to enhanced tumour cell migration, invasion and metastasis capacities." (PMID 32488136, 2020). "In the present study, we studied the role of UTMD-induced oxidative stress on the tumor EMT process and investigated that the generation of ROS induced by UTMD inhibited EMT through the regulation of miR-200c/ZEB1 axis." (PMID 32313093, 2020). "An important amount of Ki67-labelled proliferating cells was observed at the tumor periphery and the invasive fronts of the tumors where TAZ and ZEB1 were overexpressed." (PMID 32545795, 2020).
tumor (continued). "EC cells were subcutaneously inoculated into the nude mice to construct the EC tumor model, and the tumor-bearing mice were further treated with L-OHP combined with oe-LINC00152 or si-ZEB1." (PMID 33292221, 2020). "MAGI2-AS3 was identified as an EMT-related lncRNA and is highly co-expressed with ZEB1 and ZEB2 in both tumor and normal stomach tissues." (PMID 32987716, 2020). "The aim of this study was to analyze the expression of SNAIL, SLUG, TWIST1, TWIST2, ZEB1, and ZEB 2 in primary tumor and the correlation with morphological and clinical characteristics of EC." (PMID 33457409, 2020). "Zinc finger E-box-binding homeobox 1 (ZEB1), a key transcription factor to induce EMT in cancer cells, has been shown to communicate between cancer cells and TAMs for promoting tumor progression." (PMID 32283687, 2020). "Transcription factors, including Snail family members (Slug), Twist, ZEB1 and others, have been identified as critical regulators of EMT during tumor progression, embryogenesis, and metastasis." (PMID 32185181, 2020). "Additionally, in comparison with the treatment of oe-LINC00152 and si-NC plus L-OHP, the treatment of oe-LINC00152 and si-ZEB1 plus L-OHP led to decreased tumor growth rate, indicating that silencing ZEB1 could inhibit the resistance in EC induced by LINC00152 overexpression (p < 0.05)." (PMID 33292221, 2020). "As such, ZEB1 and ZEB2 are mainly considered as drivers of tumour cell invasion into distant tissues." (PMID 32796736, 2020). "Here, knock-down of ZEB1 in B16-F10 CD133+/CD44+ CSCs results in significantly reduced clonogenicity, proliferation and migratory properties in vitro and reduced tumour growth and lung tumour metastasis in vivo." (PMID 32796736, 2020). "ZEB1 is an EMT inducing transcription factor, and it is critical for tumor cell invasion and dissemination." (PMID 32408908, 2020). "Transcription factors such as SNAI2 and ZEB1 play a very important role in the process of EMT and tumor formation through inhibition of E-cadherin expression." (PMID 32605257, 2020). "Further research confirmed that by recruiting the transcription factor YB1 (Y-box binding protein 1) to the promoter region of ZEB1, BX11 is able to activate the transcription of ZEB1, thus promoting the distant metastasis of tumor cells." (PMID 33520725, 2020). "ZEB1, Twist, and Snail (EMT-related transcription factors) are directly regulated by miR-429 and miR-101 and inversely by let-7d and mediate tumor growth and metastasis in OSCC." (PMID 32547936, 2020). "Another miRNA which can radiosensitize is miR-875-5p, which is down-regulated in PCa and enhances tumor control after radiation by preventing EMT, as it indirectly targets ZEB1." (PMID 32293453, 2020). "Based on our findings, we propose that endothelial cells within the tumor function as a CSC niche by directly providing Notch1 ligands, such as Jag1, to the Notch1 receptors expressed in adjacent breast CSCs to elevate Zeb1 expression via a juxtacrine effect." (PMID 33046710, 2020). "LncRNA MAGI2-AS3 down-regulates the expression of miR-141/200a to induce ZEB1, leading to the stimulation of EMT and enhanced invasion of tumor cells." (PMID 32664703, 2020). "Two of the clusters have high expression of genes related to mesenchymal phenotype (e.g., CDH2, SNAI2, ZEB1, TWIST1, and VIM) which were assigned as tumor cells with EMT characteristics (EMT+)." (PMID 32988401, 2020). "A cadherin switch and an intermediate filaments rearrangement within primary site tumor cells together with the expression of the EMT-related transcription factors TWIST-1, ZEB-1, and HIF-1α were observed." (PMID 33297475, 2020).
tumor (continued). "First, we found a high and significant correlation between ZEB1 and SETD1B (rs = 0.523, p < 0.001) in this tumor group." (PMID 32094334, 2020). "Both ZEB1 and MYB are transcription factors that function as biological switches for molecular elements of their targets, affecting the tumor microenvironment and cell morphology." (PMID 32014049, 2020). "Conversely, silencing of ZEB1 led not only to increased levels of AGR2 protein, but also attenuated the invasiveness of tumor cells." (PMID 32570918, 2020). "miR-200a has been reported to inhibit tumor cell EMT and metastasis by suppressing the expression of ZEB1 in cancer cells." (PMID 32850368, 2020). "The transcription factor zinc-finger E-box binding homeobox 1 (ZEB1) is involved in the epithelial-to-mesenchymal transition (EMT) and plays a pivotal role in tumor metastasis." (PMID 32296027, 2020). "High expression of ZEB1 and ZEB2 at a tumor invasion front in brain metastatic tissues suggests a role of these EMT regulators in facilitating BM." (PMID 32059676, 2020). "The dual-negative regulation of ZEB1/MYC is thought to be the molecular mechanism of cell plasticity, regulating the state of tumor stem cells and promoting tumor invasion and metastasis." (PMID 32014049, 2020). "Mechanistically, SNHG6 was identified to abolish miRNA-induced repression of ZEB1 by binding miR-101-3p and inducing epithelial-mesenchymal transition (EMT), thus modulating tumor growth and metastasis." (PMID 32000704, 2020). "Evaluating the miRNA cluster involved in EMT, three transcripts coding for Vimentin, and Zinc Finger E-Box Binding Homeobox-1/-2 (ZEB1 and ZEB2), were found significantly up-regulated in resistant tumor vs. control." (PMID 33330058, 2020). "The role of expression of epithelial markers such as E-cadherin, the phenomenon of cadherin switch and overexpression of mesenchymal markers (like Snail, Twist, ZEB1/2, Slug and VIM) has been shown across tumor models." (PMID 32758253, 2020). "Our observations, where miR-142-5p targeted both SREBP1 and ZEB1 in ESCC cells, provide additional support to its role as a tumor suppressor." (PMID 31861383, 2019). "Others report the expression of EMT inducers such as ZEB1 and TWIST1 in surrounding fibroblasts, hence promoting the tumor budding phenotype." (PMID 31316988, 2019). "Down-regulating the expression of miR-200a promote tumor growth and EMT via targeting E-cadherin repressors ZEB1/ZEB2 in Wnt/β-catenin pathway." (PMID 31652445, 2019). "Taken together, the results demonstrated that miR-126 exerts tumor suppressing effects on the proliferation, migration and invasion by inhibiting MMP2, MMP9 and JAK2/STAT3 pathway via targeting ZEB1." (PMID 31007650, 2019). "MiR-1199-5p and ZEB1 form a reciprocal repressive feedback loop to potentially coordinate EMT and tumor metastasis." (PMID 30813457, 2019). "Stromal ZEB1 was present in 43.8% (43/98) of luminal, 50.0% (11/22) of HER2+ as well as 55.3% (26/47) of TNBC tumours, whereas it was detected in 10% or less of matched normal breast tissues." (PMID 31324807, 2019). "By simultaneously targeting a variety of EMT-inducing factors, including ZEB1, these important anti-metastatic miRNAs, alone or cooperatively, are sufficient to suppress EMT and tumor metastasis 23-25." (PMID 31534537, 2019). "miR-101 has been reported to act as a tumor suppressor by targeting CDH1 inhibitors, such as ZEB1/ZEB2 and EZH2 in different tumors, including GC." (PMID 31509966, 2019). "MicroRNA-200 family has also been shown to enhance EMT via targeting zinc finger E-box-binding homeobox 1 (ZEB1) axis, which is known to inhibit the tumor suppressor gene E-cadherin." (PMID 31464654, 2019). "Similar correlation analysis was conducted for mRNA expression datasets for OMA1 and mesenchymal marker genes such as TWIST1, ZEB1, and Fibronectin (FN1) using the input, TCGA_Tumor (BRCA Tumor) and TCGA_Normal (BRCA_Normal) with Pearson’s statistical test." (PMID 31611601, 2019).
tumor (continued). "The significant heterogeneity of PRMT1, ZEB1, and TWIST1 immunostaining was observed among analyzed tumor types (p < 0.001)." (PMID 31655611, 2019). "We found that ZEB1 protein was primarily present in the stromal compartment, but was largely absent in the epithelial compartment of luminal, HER2+ and TNBC tumours." (PMID 31324807, 2019). "As well, ZEB1 contributes to GBM progression, acting as a pro-tumor factor, and its expression inversely correlates with survival of GBM patients." (PMID 31905754, 2019). "CCL2 can also derive from tumor cells undergoing EMT (e.g., through ZEB1), promoting M2 polarization." (PMID 31416205, 2019). "Previous studies showed that ZEB1/ZEB2 and miR-200 family negatively regulate each other, which has important implication for EMT and tumor metastasis." (PMID 31263239, 2019). "The immunohistochemical analysis of the tumor sections showed that fatostatin-treated samples showed a markedly reduced staining for SREBP1, Ki67, ZEB1, and vimentin as compared to those in the control counterparts." (PMID 31861383, 2019). "Both western blot analysis and IHC assay confirmed that overexpression of ZEB1 significantly abrogated the gemcitabine-induced elevation of p-γH2AX and cleaced-PARP-1 in ROCK2-deletion tumor." (PMID 31783584, 2019). "As clinical behavior of tumor stage pT1 is similar to pT2, and pT3 to pT4, we analyzed the significance of PRMT1, RUNX1, ZEB1 and TWIST 1 expression in pT1/pT2 versus pT3/pT4 stage group." (PMID 31655611, 2019). "MS-275 upregulated the expression of E-cadherin and downregulated the expression of N-cadherin, as well as ZEB1, SNAIL and SLUG transcription factors in tumor tissues." (PMID 30691229, 2019). "Although ZEB1 is best known for promoting tumor progression by triggering an epithelial-to-mesenchymal transition (EMT) in cancer cells, it also plays important roles in embryogenesis—Zeb1 (-/-) mice die before birth—and cell differentiation." (PMID 30304480, 2018). "Our results thus show that disrupting the in vivo regulation of Zeb1 by miR-200c is sufficient to drive EMT, thus highlighting the importance of this axis in tumor progression and invasion and its potential as a therapeutic target." (PMID 30405106, 2018). "Along with ZEB1, ZEB2 is reported to localize to the cytoplasm as well as to the nucleus, and the subcellular localization of ZEB2 is regulated in normal and tumor tissues, suggesting that ZEB2 functions are regulated by means of its subcellular localization." (PMID 29416649, 2018). "The possible role of EMT in tumor propagation was substantiated by the expression of a variety of markers described to be involved in EMT, such as Zeb1 and CD146/MCAM." (PMID 29171037, 2018). "MiR-200c is a regulator of epithelial-to-mesenchymal transition which targets the transcriptional repressors of E-cadherin, ZEB1 and ZEB2, suggesting a tumor suppressive function." (PMID 30473751, 2018). "Several multipotent TFs, such as Twist1/2, Snail1/2 and Zeb1/2 play key roles in the regulation of EMT program and tumor metastasis." (PMID 30038287, 2018). "A negative correlation between miR-200a-3p and CDK6 transcription and a positive correlation between circ-ZEB1.33 and CDK6 transcription were found within HCC tumor tissues." (PMID 30123094, 2018). "Several studies proved the relationship between E-Cadherin, β-catenin, snail, ZEB1, ZEB2 expression and tumor budding using immunochemistry, and drew the conclusion of EMT induction at the tumor–host interface, but more evidence are required." (PMID 27999192, 2017). "In considering both tumor and normal samples, miR-34a was inversely correlated with NOTCH1 (r = −0.563, P = 0.001), SLUG (r = −0.374, P = 0.009), ZEB1 (r = −0.505, P = 0.001), and ZEB2 (r = −0.317, P = 0.028) expressions." (PMID 28423483, 2017).